CD59 (CD59 molecule (CD59 blood group))
Description:
Potent inhibitor of the complement membrane attack complex (MAC) action, which protects human cells from damage during complement activation. Acts by binding to the beta-haipins of C8 (C8A and C8B) components of the assembling MAC, forming an intermolecular beta-sheet that prevents incorporation of the multiple copies of C9 required for complete formation of the osmolytic pore. The soluble form from urine retains its specific complement binding activity, but exhibits greatly reduced ability to inhibit complement membrane attack complex (MAC) assembly on cell membranes.
Synonyms: HRF-20; HRF20; MAC-IP; MACIF; MIRL; MIC11; MIN1; MIN2; MIN3; MSK21; 16.3A5; EJ16; EJ30; EL32; G344; p18-20; 1F5; MEM43
Tractability: Antibody: UniProt places it where antibodies can reach, with high confidence; its Gene Ontology location is reachable by antibodies, with high confidence; UniProt predicts a signal peptide or a membrane-spanning region. PROTAC: ubiquitination databases record sites on it; its protein half-life has been measured.
Gene: Protein-coding gene on chromosome 11 (33,703,010 to 33,736,639, reverse strand). Ensembl gene ENSG00000085063.
Subcellular location: Cell membrane; Secreted
Subcellular location (Human Protein Atlas): Golgi apparatus; Vesicles
Pathways (Reactome):
Vesicle-mediated transport: COPI-mediated anterograde transport; COPII-mediated vesicle transport; Cargo concentration in the ER
Immune System: Neutrophil degranulation; Regulation of Complement cascade
Gene Ontology:
Molecular function: protein binding; protein sequestering activity; complement binding
Biological process: negative regulation of activation of membrane attack complex; negative regulation of complement activation; negative regulation of complement-dependent cytotoxicity; regulation of complement activation; regulation of complement-dependent cytotoxicity; blood coagulation; cell surface receptor signaling pathway
Cellular component: cell surface; external side of plasma membrane; extracellular exosome; extracellular region; focal adhesion; plasma membrane; vesicle; endoplasmic reticulum membrane; endoplasmic reticulum-Golgi intermediate compartment membrane; ER to Golgi transport vesicle membrane; Golgi membrane; membrane; specific granule membrane; tertiary granule membrane; transport vesicle
Genetic constraint (gnomAD): Loss-of-function variants: 0 observed, 2.17 expected, observed/expected ratio (o/e) 0, 90% interval 0 to 1.28. That is too few expected variants to judge how well the gene tolerates losing a copy. Missense variants: 99 observed, 113.55 expected, observed/expected ratio (o/e) 0.87, 90% interval 0.74 to 1.03. Synonymous variants: 44 observed, 49.28 expected, observed/expected ratio (o/e) 0.89, 90% interval 0.7 to 1.15.
Homologues: Orthologues: macaque CD59 (70% identical), dog CD59 (46% identical), rabbit CD59 (46% identical), rat Cd59b (44% identical), mouse Cd59b (42% identical), mouse Cd59a (38% identical). Paralogues in human: LYPD2 (27% identical), LYPD1 (23% identical), SLURP1 (23% identical).
Diseases named in the same sentence as CD59 in open-access papers:
CD59 is named in the same sentence as 232 diseases in open-access papers, as found by Europe PMC text mining. Sharing a sentence is not in itself a finding about the gene and the disease. The quoted sentences say what the papers report.
paroxysmal nocturnal hemoglobinuria (59 papers, 2009 to 2026). Paroxysmal nocturnal hemoglobinuria (PNH) is an acquired clonal hematopoietic stem cell disorder characterized by corpuscular hemolytic anemia, bone marrow failure and frequent thrombotic events. "Conversely, in patients with paroxysmal nocturnal hemoglobinuria, where CD59 (and CD55) are deficient, RBCs become highly susceptible to intravascular hemolysis." (PMID 41431006, 2025). "Clinically, deficiency of CD59 is responsible for the development of paroxysmal nocturnal hemoglobinuria (PNH), as noted by increased susceptibility of erythrocytes to complement-mediated lysis." (PMID 31739586, 2019). "Deficiency in CD55 and CD59 is associated with paroxysmal nocturnal haemoglobinuria (PNH), which is associated with complement-mediated haemolysis and thrombosis." (PMID 24278688, 2012). "A deficiency of MCP has been associated with atypical human uraemic syndrome (aHUS) which is characterized by thrombotic microangiopathies, while a deficiency of DAF/CD59 is associated with paroxysmal nocturnal haemoglobinuria (PNH), which also is associated with thrombosis." (PMID 30116749, 2018). "Flow cytometry confirmed a deficiency of CD55 and CD59, diagnostic of paroxysmal nocturnal hemoglobinuria (PNH)." (PMID 41450399, 2025). "The spectrum of clinical presentations associated with complement dysregulation also includes protein-losing enteropathy (CD55 deficiency) and paroxysmal nocturnal hemoglobinuria (PNH) (CD55+CD59 deficiency)." (PMID 34434189, 2021). "For instance, deficiency in complement regulators CD55 and CD59, leads to paroxysmal nocturnal hemoglobinuria (PNH), whereas Factor H mutations predispose to atypical hemolytic uremic syndrome (aHUS), both causing severe thrombohemolysis." (PMID 32793201, 2020). "These include angioedema (C1 inhibitor [C1-INH] deficiency), kidney and eye diseases (FH, FI or CD46 deficiency), protein-losing enteropathy (CD55 deficiency) and paroxysmal nocturnal hemoglobinuria (PNH) (CD55 + CD59 deficiency)." (PMID 32064578, 2020). "Acquired CD59 deficiency is well known in paroxysmal nocturnal hemoglobinuria (PNH), where a clonal defect in GPI biosynthesis confined to the hematological system, results in hemolysis and prothrombotic tendency." (PMID 30794663, 2019). "Flow cytometry showed 57% CD59 deficient red blood cells, 88% CD157 deficient monocytes, and 91% CD157 deficient neutrophils, consistent with a new diagnosis of paroxysmal nocturnal hemoglobinuria (PNH)." (PMID 42257063, 2026). "FCM analysis performed on peripheral blood demonstrated CD55(−) CD59(−) granulocytes (approximately 42%) and red blood cells (approximately 16%), consistent with paroxysmal nocturnal hemoglobinuria (PNH)." (PMID 39910008, 2025). "Inadequate CD59 activity can result in excessive complement activation, leading to various known disorders, including paroxysmal nocturnal hemoglobinuria (PNH), an acquired hematological disorder characterized by the destruction of red blood cells." (PMID 39518137, 2024). "Inherited mutations of the regulatory protein CD59 cause loss of CD59 on the red blood cell (RBC) surface and are linked with the development of paroxysmal nocturnal hemoglobinuria (PNH), causing intravascular hemolysis and thrombosis." (PMID 38406130, 2024). "In patients with paroxysmal nocturnal hemoglobinuria (PNH), autologous complement activation has been demonstrated as a result of CD59 and DAF deficiency, inhibiting MAC formation resulting in hemolysis." (PMID 32923410, 2020). "After exclusion of Fanconi anemia (no spontaneous and diepoxybutane‐induced chromosome breakage) and paroxysmal nocturnal hemoglobinuria (normal CD55/CD59 expression in granulocytes and erythrocytes), a diagnosis of idiopathic aplastic anemia was made." (PMID 29191945, 2018).
paroxysmal nocturnal hemoglobinuria (continued). "Paroxysmal nocturnal hemoglobinuria (PNH) is a rare, X-linked blood disorder in which red blood cells lack the GPI-APs CD55 and CD59 due to somatic mutations in a gene (phosphatidylinositol glycan class A, PIGA)." (PMID 28785375, 2017). "Differences in the expression level of CD59 have a strong influence on complement activity: genetic deficiencies in GPI expression prevent cellular trafficking and surface expression of CD59, which results in paroxysmal nocturnal hemoglobinuria." (PMID 35563599, 2022). "In the context of acquired BMF syndromes, paroxysmal nocturnal hemoglobinuria (PNH) is a clonal disease caused by a somatic mutation in the PIGA-gene resulting in the deficiency of GPI-anchored proteins (such as CD55 and CD59) and leads to erythrocytes unable to control complement activation." (PMID 36439498, 2022). "Paroxysmal nocturnal hemoglobinuria (PNH) is a hematological disorder caused by a deficiency in glycosylphosphatidylinositol anchor synthesis that negatively affects the expression of the CRPs CD55 and CD59." (PMID 34359708, 2021). "Paroxysmal nocturnal hemoglobinuria (PNH) is a disease that involves hemolysis caused by the lack of CD55- or CD59-mediated complement activity inhibition in the absence of GPI anchor on the surface of red blood cells." (PMID 24455465, 2014). "In fact, downregulation or lack of CD55 and CD59 expression is associated with clinical diseases including paroxysmal nocturnal hemoglobinuria and dysferlin-deficient muscular dystrophy." (PMID 25254972, 2014). "CD55 and CD59 were expressed normally on erythrocyte, granulocyte and monocyte, which excluded the diagnosis of paroxysmal nocturnal hemoglobinuria (PNH)." (PMID 41472573, 2026). "However, caution should be taken, as adverse CD-59 blockade may cause paroxysmal nocturnal hemoglobinuria (PNH), which is characterized by elevated complement activity, RBCs lysis and CD-59 decreased expression." (PMID 33344222, 2020). "RBCs of patients with paroxysmal nocturnal hemoglobinuria (PNH) lack the GPI-anchored proteins CD55 and CD59 that protect against complement activation-associated hemolysis." (PMID 29937736, 2018). "Somatic PIGA mutations cause paroxysmal nocturnal hemoglobinuria (PNH) (MIM 300818), an acquired complement‐mediated hemolytic disease resulted from loss of GPI‐anchored CD55 and CD59 on erythrocytes." (PMID 29974678, 2018). "The model simulations, via reduction in FH and CD59, reflect the mechanistic basis of complement activation in diseases such as atypical hemolytic uremic syndrome (aHUS) and paroxysmal nocturnal hemoglobinuria (PNH)." (PMID 35517827, 2022). "Our group generated disease-free iPSCs from the fibroblasts of a patient with paroxysmal nocturnal hemoglobinuria (PNH), whose granulocytes and red blood cells consist of a minor normal population and major population with decreased surface CD55 and CD59." (PMID 34831472, 2021). "CD59 is an essential regulator that prevents unwanted complement activation on host cells, as illustrated by the hemolysis seen in CD59 knockout mice and in paroxysmal nocturnal hemoglobinuria (PNH)." (PMID 33306183, 2021). "This is the case in paroxysmal nocturnal hemoglobinuria (PNH), where a proportion of bone marrow-derived cells lack GPI-anchored CD59 and CD55." (PMID 24119446, 2013). "Mutations in another enzyme in the GPI synthesis pathway, PIGA, cause paroxysmal nocturnal hemoglobinuria, in which hematopoietic stem cells produce RBCs lacking CD55 and CD59, 2 surface proteins that prevent RBCs hemolysis." (PMID 41431006, 2025). "Paroxysmal nocturnal hemoglobinuria (PNH) is a rare, acquired clonal hematologic disorder caused by somatic mutations in the PIGA gene of hematopoietic stem cells, leading to the absence of GPI-anchored proteins, including the complement regulators CD55 and CD59." (PMID 41002734, 2025).
paroxysmal nocturnal hemoglobinuria (continued). "Assessment of peripheral blood flow cytometry for CD55 and CD59 was negative, which excludes paroxysmal nocturnal hemoglobinuria (PNH)." (PMID 40703529, 2025). "The transfer of exosomal CD59 from prostasomes to red cells lacking CD59 (rabbit erythrocytes and human erythrocytes from patients with paroxysmal nocturnal hemoglobinuria) indeed proved to induce protection against complement-mediated hemolysis." (PMID 29951375, 2018). "ECU can effectively prevent hemolysis in paroxysmal nocturnal hemoglobinuria (PNH) caused by a lack of complement-regulating CD55 and CD59 on blood cells." (PMID 24086391, 2013). "Interestingly, CD59 exposure was not reduced on RBCs surfaces compared to those of healthy controls, as is typically observed in paroxysmal nocturnal hemoglobinuria." (PMID 41431006, 2025). "Paroxysmal nocturnal hemoglobinuria (PNH) is a rare, chronic, and potentially life-threatening hematological disorder caused by genetic mutations that lead to the absence of complement regulatory proteins CD55 and CD59 on red blood cells." (PMID 40430547, 2025). "Patients with paroxysmal nocturnal hemoglobinuria (PNH) have defective complement regulators, CD55 and CD59, and an increased incidence of adverse pregnancy outcomes." (PMID 32849586, 2020). "This treatment was initially registered for patients with paroxysmal nocturnal hemoglobinuria (PNH), where an acquired defect in the glycophosphoinositol-anchored natural complement inhibitors, CD55 and CD59 leads to complement-mediated hemolysis." (PMID 25688346, 2015). "In paroxysmal nocturnal hemoglobinuria (PNH), acquired mutations in the phosphatidylinositol glycan class A gene on hematopoietic stem cells lead to a loss of CD55 and CD59, important negative complement regulators on red cell membranes." (PMID 40338657, 2025). "Defects in the biosynthesis of GPI causes paroxysmal nocturnal hemoglobinuria (PNH), a hematological disease characterized by increased intravascular hemolysis and complement activation due to the absence of CD55 and CD59." (PMID 31417415, 2019). "Paroxysmal nocturnal hemoglobinuria (PNH) is a rare and progressive hematopoietic stem cell disorder in which hematopoietic cells are deficient in glycosylphosphatidylinositol (GPI), which leads to a lack of the complement inhibitor proteins CD55 and CD59 on the surface of blood cells." (PMID 24587926, 2014). "ECU is a monoclonal anti-C5 antibody which inhibits C5 activation, thus blocks the terminal pathway of the complement system irrespective of lacking CD55 and CD59 on peripheral blood cells and is most effective in paroxysmal nocturnal hemoglobinuria (PNH)." (PMID 24086391, 2013). "Immunophenotyping in the peripheral blood revealed normal CD55 and CD59 expression and paroxysmal nocturnal hemoglobinuria (PNH) was not considered." (PMID 20062604, 2009). "Consequently, the autoimmune antibody, fluorescently labeled modified aerolysin (FLAER), CD55\CD59 expression, and direct antiglobulin (Coombs) tests were not abnormal, which ruled out paroxysmal nocturnal hemoglobinuria (PNH) and autoimmune hemolytic anemia." (PMID 33592896, 2021).
prostate carcinoma (21 papers, 2010 to 2025). A carcinoma that arises from epithelial cells of the prostate gland. "Several of the identified cell surface markers have known associations with prostate cancer and metastasis including CD59, 4F2 cell-surface antigen heavy chain (SLC3A2) and adhesion G protein-coupled receptor E5 (CD97)." (PMID 38053024, 2023). "CD59 has previously been detected in blood plasma and urine EVs from prostate cancer patients, as well as in blood plasma EVs from colorectal cancer patients, suggesting that CD59 is predominantly an EV cargo protein associated with later stages of cancer." (PMID 38938900, 2023). "In particular, the expression of CD55 and CD59 on PrC cells may be associated with promoting cell survival and contributing to the metastatic potential of prostate cancer cells." (PMID 40733075, 2025). "Using a CRISPRi screen and mass spectrometry, we identified CD59 as a candidate Siglec-9 ligand in prostate cancer." (PMID 39436703, 2024). "The identification of Siglec-7 and -9 as potential therapeutic targets, including the CD59/Siglec-9 axis, opens up opportunities for immune-based interventions in prostate cancer." (PMID 39436703, 2024). "Recent studies have shown that significantly lower CD59 correlates with poor survival in breast cancer, while high expression of CD59 protein induced decreased overall survival rates in colorectal cancer, prostate cancer, etc.." (PMID 36294966, 2022). "Similar results were obtained in another study that compared 40 biopsies of prostate cancer patients with 40 biopsies of benign prostatic hyperplasia and assessed a sharp increase in CD59 expression and colocalization with PTX3." (PMID 34572075, 2021). "In a cohort of 86 primary adenocarcinomas, CD59 protein expression was detected in epithelia of prostate cancer, prostatic intraepithelial neoplasia, benign hyperplasia, atrophic, and normal glands." (PMID 34572075, 2021). "NF-κB can also stimulate the expression of CD59, and increased CD59 expression by prostate cancer cells can help them evade the immune system and promote their growth and metastasis." (PMID 32337233, 2020). "hBMSCs and hFOB1.19 cells modulate the phenotype of PC3 prostate cancer cells and the expression of CD59 by activating the RANK/RANKL/OPG signaling pathway." (PMID 32337233, 2020). "Next, on the basis of this study, we will further study the effect of CD59 expression on bone metastasis of prostate cancer cells." (PMID 32337233, 2020). "Increased expression of CD59 in prostate cancer cells can facilitate evasion of the immune system, which is conducive to their growth in the bone/bone marrow microenvironments." (PMID 32337233, 2020). "CD59 and haptoglobin were up-regulated in prostate cancer with bone metastasis while tetranectin was down-regulated." (PMID 31413735, 2019). "It has been verified that CD59, haptoglobin and tetranectin are prostate cancer bone metastasis related proteins." (PMID 31413735, 2019). "Local tumor progression and tissue dedifferentiation of prostate cancer also correlate with CD59 expression." (PMID 31024572, 2019). "In this study, we analyzed the expression of CD59 in prostate cancer cell lines DU145, LNCap and PC3." (PMID 31413735, 2019). "By immunohistochemical staining, we found that CD59 was expressed in cell membrane and cytoplasm of prostate cancer epithelial cells, and positive staining particles were found in the cytoplasm." (PMID 31413735, 2019). "K562 erythroleukemia cells and breast, ovarian, and prostate carcinoma cell lines secrete soluble CD59." (PMID 31024572, 2019). "Because PC3 cell line is from bone metastasis of a prostate cancer patient, this indicates that CD59 has a high correlation with bone metastasis of prostate cancer." (PMID 31413735, 2019).